MDK (midkine)
Diseases named in the same sentence as MDK in open-access papers (continued):
Sharing a sentence is not in itself a finding about the gene and the disease.
lymphopenia (1 paper, 2025). Reduction in the number of lymphocytes. "GM-CSF, another MDK-induced cytokine, supports the expansion of immunosuppressive myeloid populations in GBM through IL-4R alpha and is associated with the tumor’s characteristic lymphopenia and systemic immune dysfunction." (PMID 40835683, 2025).
medulloblastoma (1 paper, 2024). A malignant, invasive embryonal neoplasm arising from the cerebellum. "Midkine signalling was more active in LFS compared to sporadic medulloblastomas (two-fold higher score for cell-cell communication), suggesting a critical role for this pathway for the communication between cell populations in LFS medulloblastoma." (PMID 39609432, 2024). "This analysis identified midkine signalling as a major signalling pathway in LFS medulloblastoma." (PMID 39609432, 2024). "The midkine ligand MDK was expressed by malignant cells, as shown in matched scRNA-seq data of the same LFS medulloblastomas." (PMID 39609432, 2024).
meningioma (1 paper, 2023). A generally slow growing tumor attached to the dura mater. "When human meningioma cells were treated with camptothecin, there was a decrease in active caspase-3 in the human meningioma cells, those that overexpressed MDK." (PMID 37240085, 2023).
metastatic cancers to (1 paper, 2017). "Relative low specificity of midkine as a marker is associated with lack of tumor type specificity of the midkine expression, and the elevated levels in metastatic cancers to pleura are attributable to the growth-linked property." (PMID 28335760, 2017).
microhematuria (1 paper, 2024). "Among the biomarkers, MDK showed the best AUC, 0.760, for the detection of UBC, followed by KRT17 with AUC 0.730, and both EV mRNA markers outperformed conventional markers such as cytology (AUC 0.721), NMP22 (AUC 0.692), microhematuria (AUC 0.669) and BTA (AUC 0.659)." (PMID 38514751, 2024).
minimal change disease (1 paper, 2025). "Conversely, MDK was significantly upregulated in several inflammatory and metabolic kidney diseases, except for minimal change disease." (PMID 40663403, 2025).
myxoma (1 paper, 2024). A benign soft tissue neoplasm characterized by the presence of spindle and stellate cells, lobulated growth pattern, and myxoid stroma formation. "We found that MDK was primarily expressed by myxoma tumour cells, and was significantly overexpressed when compared to left atrial fibroblasts in normal hearts." (PMID 38318640, 2024). "The hyperactive signals in many malignant tumours, such as MDK, HGF, chemerin and GDF15 signalling, were found to be sent primarily by myxoma tumour cells." (PMID 38318640, 2024).
neuromyelitis optica (1 paper, 2023). A rare inflammatory disease of the central nervous system characterized mainly by attacks of uni- or bilateral optic neuritis (ON) and acute myelitis. "In autoimmune CNS disorders like neuromyelitis optica (NMO) and MS, increased levels of MDK have been associated to a poor prognosis." (PMID 38098484, 2023).
oesophageal cancer (1 paper, 2023). "Through correlation analysis using data from TCGA and GTEx, the expression level of MDK was significantly correlated with NCL in human oesophageal cancer and paratumour oesophageal tissues." (PMID 36855810, 2023). "The results suggested the expression level of MDK in human oesophageal cancer was more than eight times higher than that in paratumour tissue, and the expression of NCL was also slightly increased in human oesophageal cancer." (PMID 36855810, 2023). "Therefore, the hypothesis that MDK in oesophageal cancer cells could interact with NCL on the surface of CAFs to upregulate the proliferation of CAFs was proposed." (PMID 36855810, 2023). "Therefore, it was hypothesised that MDK in oesophageal cancer cells could interact with NCL on the surface of CAFs to upregulate the proliferation of CAFs." (PMID 36855810, 2023).
osteosarcoma (1 paper, 2023). A usually aggressive malignant bone-forming mesenchymal neoplasm, predominantly affecting adolescents and young adults. "Inhibition of MDK by anti-MDK antibody suppressed osteosarcoma cell proliferation and reduced tumor growth in vivo, and also significantly reduced lung metastasis of osteosarcoma." (PMID 37240085, 2023). "Growth inhibition of osteosarcoma cells was seen after treatment with functional anti-MDK antibody." (PMID 37240085, 2023).
ovarian tumors (1 paper, 2019). "EHMK‐51‐35 carrier cells infected with AdE3‐midkine or co‐infected with AdE3‐mikine and Ad‐mGM‐CSF were injected three times into subcutaneous OVHM ovarian tumors in syngeneic mice." (PMID 30548997, 2019).
pilocytic astrocytoma (1 paper, 2020). Pilocytic astrocytoma is a rare subtype of low-grade glioma of the central nervous system characterized by a well circumscribed, often cystic, brain tumor with a discrete mural nodule and long, hair-like projections that extend from the neoplastic astrocytes. "Relevant to human and mouse NF1-LGG, we also examined MDK expression in the Nf1 OPG mice and human NF1-LGG (pilocytic astrocytoma; PA) samples." (PMID 32358581, 2020).
Portal vein thrombosis (1 paper, 2024). Thrombosis of the portal vein and/or its tributaries, which include the splenic vein and the superior and inferior mesenteric veins. "Interestingly, however, MDK exhibited higher levels in patients with multiple focal lesions, lesions exceeding 5 cm, and those with portal vein thrombosis, compared with those with single focal lesions, lesions smaller than 5 cm, and those without portal vein thrombosis." (PMID 38247828, 2024).
renal carcinoma (1 paper, 2025). A carcinoma arising from the epithelium of the renal parenchyma or the renal pelvis. "In renal cancer, M2 TAMs are twice as prevalent as in normal tissue, promoting metastasis through midkine (MDK) and chemokines like CXCL13." (PMID 40361374, 2025).
retinal degeneration (1 paper, 2025). Degeneration of the retina. "Relative to VEGF, the heparin-binding growth factors MDK/PTN are poorly studied in retinal degenerations." (PMID 40251274, 2025).
retinoblastoma (1 paper, 2016). A malignant tumor that originates in the nuclear layer of the retina. "Insulin growth factor 2 mRNA binding protein 1 (IGF2BP1), chromogranin A, fetuin A (ASHG), Rac GTPase-activating protein 1 and midkine that were found to be overexpressed in retinoblastoma were further confirmed by immunohistochemistry by staining 15 independent retinoblastoma tissue sections." (PMID 27799869, 2016).
rhabdoid tumor (1 paper, 2013). An aggressive malignant embryonal neoplasm usually occurring during childhood. "In human pediatric rhabdoid tumor G401 cells, midkine activates the anti-apoptotic pathway mediated by STAT1 and the Janus-activated kinases (JAKs)." (PMID 24083030, 2013).
Right ventricular hypertrophy (1 paper, 2020). In this case the right ventricle is more muscular than normal, causing a characteristic boot-shaped (coeur-en-sabot) appearance as seen on anterior- posterior chest x-rays. "Hypoxia-induced pulmonary arterial remodeling and right ventricular hypertrophy were attenuated in midkine-knockout mice." (PMID 32587339, 2020).
sarcoma (1 paper, 2018). A usually aggressive malignant neoplasm of the soft tissue or bone. "Some of the genes identified already have a well-established connection to human sarcomas, including ORAOV1, SSX5, NKX2, XAGE1, MDK and CCND1." (PMID 30093970, 2018).
schizophrenia (1 paper, 2023). A major psychotic disorder characterized by abnormalities in the perception or expression of reality. "Chromosome 11p11 also harbours genes that have been previously associated with schizophrenia and/or brain structural phenotypes, including CHRM4, MDK, AMBRA1 and HARBI127,66,67." (PMID 38016951, 2023).
stricture (1 paper, 2025). "MDK–NCL, CXCL5/6‐CXCR2, and TGFA–EGFR ligand–receptor pairs were enhanced in stricture tissues, mediating epithelial–stromal interactions." (PMID 39910700, 2025).
systemic sclerosis (1 paper, 2018). A chronic disorder, possibly autoimmune, marked by excessive production of collagen which results in hardening and thickening of body tissues. "MDK and FSTL3 were also examined in other clinical subgroups of systemic sclerosis and were shown to be specifically upregulated compared to dcSSc, lcSSc-ILD (diagnosed by HRCT), healthy controls were included for reference." (PMID 30115106, 2018).
teratocarcinoma (1 paper, 2008). A germ cell tumor characterized by the presence of an embryonal carcinoma component and a teratoma component. "MDK was first identified as a retinoic acid-responsive gene in the teratocarcinoma stem cells." (PMID 18275606, 2008). "Unlike in the teratocarcinoma stem cells, RA did not induce MDK expression in LNCaP cells." (PMID 18275606, 2008).
thyroid nodule (1 paper, 2016). A small circumscribed mass in the THYROID GLAND that can be of neoplastic growth or non-neoplastic abnormality. "The present study explored the usefulness of midkine as a biomarker in the differentiation between benign and malignant thyroid nodules in samples from serum and FNAC." (PMID 27446208, 2016).
ulcers (1 paper, 2025). "Notably, we observed increased fibroblast-to-immune signaling through the midkine (MK), hepatocyte growth factor (HGF), IGF-binding protein (IGFBP), and KIT (stem cell factor) pathways in GK-high ulcers." (PMID 41583446, 2025).
Vestibular schwannoma (1 paper, 2025). A vestibular schwannoma (also known as acoustic neuroma, acoustic neurinoma, or acoustic neurilemoma) is a benign, usually slow-growing tumor that develops from the VIIIth cranial nerve supplying the inner ear. "Our cell communication analysis based on the curated receptor-ligand pair database showed that fibroblast in vestibular schwannoma microenvironment mainly regulated the biological behavior of tumor cells through PSAP/GPR37L1, MDK/(ITGA6 + ITGB1), IGF2/(ITGA6 + ) and MDK/LRP1 signaling axes." (PMID 40629113, 2025).
vitamin D deficiency (1 paper, 2022). A nutritional condition produced by a deficiency of VITAMIN D in the diet, insufficient production of vitamin D in the skin, inadequate absorption of vitamin D from the diet, or abnormal conversion of vitamin D to its bioactive metabolites. "There are no reports of an effect of vitamin D3 on MDK in cancer, but this seems feasible as higher levels of MDK are reported in vitamin D deficiency." (PMID 35445563, 2022).
tumor (229 papers, 2007 to 2026). "Inflammatory and tumor-associated biomarkers, including IL-17, NF-κB, and MDK, were significantly modulated following treatment." (PMID 41898364, 2026). "Previous studies have implicated MDK (Midkine) in promoting tumor angiogenesis and metastasis in various cancers." (PMID 39944338, 2025). "Not only does MDK promote macrophage/monocyte migration, MDK has been repeatedly linked to promoting M2 polarization of macrophages into tumor-associated macrophages." (PMID 40429950, 2025). "Elevated MDK levels are frequently associated with aggressive tumor behavior and poor clinical outcomes." (PMID 40500394, 2025). "In a malignant context, several cell types have been found to produce and secrete MDK, including tumor cells, cancer-associated fibroblasts, and immune cells." (PMID 40429950, 2025). "Stratifying the dataset based on IDH mutation status revealed that MDK expression is low and relatively stable across different tumor grades in IDHmutant tumors." (PMID 40835683, 2025). "We observed that the high MDK-NCL expression group exhibited higher tumor mutation burden (TMB) and microsatellite instability (MSI) scores, indicating increased genomic instability." (PMID 40396179, 2025). "MDK overexpression frequently occurs in women’s cancers and is linked to aggressive tumor behavior, treatment resistance, and metastasis." (PMID 40429950, 2025). "Accumulating studies have demonstrated that MDK signaling promotes the polarization of tumor-associated macrophages (TAMs) toward an immunosuppressive M2 phenotype." (PMID 41246334, 2025). "MDK is implicated as a critical factor in cancers by promoting cell proliferation, suppressing cell death, and ultimately promoting tumor growth." (PMID 40429950, 2025). "For example, midkine growth factor (encoded by MDK) is known to be highly expressed in numerous malignant tumours and plays diverse roles in the tumour development." (PMID 38318640, 2024). "MDK expression was upregulated in tumor tissue and was associated with lower recurrence-free and overall survival (OS) rates in this study." (PMID 37743493, 2023). "A significant association between high expression of MDK and clinically advanced tumor stage was found in BTC (T3/T4 vs. T1/T2; p = 0.007)." (PMID 37240085, 2023). "Midkine is significantly upregulated in tumor tissues and serum samples of HCC patients, and associated with poor overall survival." (PMID 36906597, 2023). "We validated differentially expressed proteins at the transcriptional level in clinical tumor specimens, association with patient survival, and absolute concentration to yield three biomarker candidates: MDK, GDF15, and SPINT2." (PMID 38260835, 2023). "Strong MDK expression was also associated with AJCC tumor stage (p = 0.004), lymph node metastases (p < 0.001), ENE (p < 0.001), and AT1R expression (p < 0.001)." (PMID 37743493, 2023). "In the current study, MDK expression was associated with advanced tumor stage, lymph node metastases, and extra-nodal extension." (PMID 37743493, 2023). "We further noted increased expression of midkine (MDK), a growth factor associated with tumor progression." (PMID 37137901, 2023). "Another example is MDK (encodes a secreted growth factor): its upregulation correlated with a worse prognosis and chemotherapy resistance in diverse malignant tumours including HCC." (PMID 33541355, 2021). "MDK is a small exosomal molecule that has been reported to be expressed in a variety of tumours and is associated with angiogenesis." (PMID 34759262, 2021). "Mechanistically, dsRNA nanoplexes were found to exert a rapid dual action in tumor cells and in their associated lymphatic vasculature, involving the transcriptional repression of the lymphatic drivers Midkine and Vegfr3, respectively." (PMID 34762341, 2021).
tumor (continued). "Antagonizing MDK slowed tumor cell growth, and further investigation showed that suppressing MDK restored the susceptibility of tumor cells to DNA damage and the mechanisms that weed out damaged cells." (PMID 31811117, 2019). "All these data provided strong evidence that high expression of MDK was closely associated with tumor angiogenesis in NPC." (PMID 30001734, 2018). "MDK was associated with the greatest number of aggressive clinical and tumour characteristics such as poor Child-Pugh status (P = 0.01), advanced BCLC stage (P = 0.006), vascular invasion (P = 0.007) and high tumour number (P = 0.007)." (PMID 27219517, 2016). "MDK has also been linked to the regulation of other members of the tumor immune environment." (PMID 40429950, 2025). "However, in many pathological processes, including tissue ischemia, inflammation, and tumours, MDK expression is often increased, and high levels of MDK expression are often associated with disease progression." (PMID 40468625, 2025). "MDK’s role in angiogenesis and therapy resistance has been confirmed through angiogenesis-related analyses associated with prognosis and tumor immune microenvironment, as well as single-cell RNA sequencing studies identifying molecular biomarkers predicting progression to CDK4/6 inhibition." (PMID 41139924, 2025). "MDK’s suppressive effects on T cells may occur indirectly through the activity of tumor-associated macrophages, MDSCs, or other immunosuppressive cells rather than direct action of MDK." (PMID 40429950, 2025). "Particularly, the MDK signaling pathway demonstrated stronger activity in the high-risk group, with bidirectional signal exchanges established between high-risk cancer cells and hepatocytes, potentially promoting tumor growth and microenvironment remodeling." (PMID 41200185, 2025). "Unlike TGF-β-mediated immunosuppression, which primarily acts via Treg activation and myeloid suppression, MDK-NCL signaling may establish a distinct immunosuppressive niche by interacting with tumor-associated macrophages (TAMs) and fibroblasts." (PMID 40396179, 2025). "Furthermore, two studies have shown MDK levels to be correlated with a tumor size greater than 5 cm and it is also associated with high recurrence rates." (PMID 38247828, 2024). "Although the functions of MDK in the context of solid tumors inside and outside the CNS exhibit remarkable similarities, it still remains unclear if the tumor promoting effects of MDK on peripheral and central neoplasms underlie a common mechanism." (PMID 38098484, 2023). "Therefore, the activated MDK–NCL signal is an important hallmark in the change of tumour microenvironment when invasion and metastasis occur shortly with the help of proliferative CAFs." (PMID 36855810, 2023). "There are many kinds of tumor-specific promoters, including those for the genes encoding human telomerase reverse transcriptase (hTERT), midkine, cyclooxygenase-2, and survivin; insertion of each of these promoters can selectively enhance the replication of adenovirus in tumor cells." (PMID 32085583, 2020). "Midkine expression in tumors was associated with cell proliferation because the transcriptional activity was dependent on cell growth and down-regulation of the expression decreased tumor cell growth." (PMID 28335760, 2017). "Active MDK signal transduction in the high-risk group may indicate that these tumor cells possess stronger proliferative capacity, angiogenic potential, and microenvironmental regulatory ability, thereby promoting invasive tumor growth and distant metastasis." (PMID 41200185, 2025). "Pharmacological inhibition of MDK also suppressed tumor growth with increased CD8+ T cell infiltration." (PMID 41833003, 2026). "Single-cell analysis showed SLC10A3 enrichment in tumor-associated astrocytes and macrophages, with enhanced astrocyte-macrophage crosstalk through MIF, MDK, and extracellular matrix remodeling pathways." (PMID 42211491, 2026).